LINC02432 (long independently transcribed non-coding RNA 2432)
Gene: Long non-coding RNA gene on chromosome 4 (141,302,910 to 141,357,096, reverse strand). Ensembl gene ENSG00000248810.
Diseases named in the same sentence as LINC02432 in open-access papers:
LINC02432 is named in the same sentence as 2 diseases in open-access papers, as found by Europe PMC text mining. Sharing a sentence is not in itself a finding about the gene and the disease. The quoted sentences say what the papers report.
hepatocellular carcinoma (1 paper, 2023). A malignant tumor that arises from hepatocytes. "Similarly, the LINC02432/hsa-miR-98–5p/HK2 axis also correlated with SIGLEC15 regulation in hepatocellular carcinomas (HCC)." (PMID 37869015, 2023).
LINC02432 also shares sentences with these, for which no sentence is quoted: glioma (1 paper).